FGF23 (fibroblast growth factor 23)
Diseases named in the same sentence as FGF23 in open-access papers (continued):
Sharing a sentence is not in itself a finding about the gene and the disease.
endothelial dysfunction (continued). "This could be explained by the multifactorial nature of CVD among CKD patients, including unique risk-factors such as increased oxidative stress, endothelial dysfunction, elevated FGF23, and accelerated vascular calcifications." (PMID 36273098, 2022). "Interestingly, a recent study in patients with CKD demonstrated a link between levels of ADMA and fibroblast growth factor-23 (FGF-23), which by itself is also linked to markers of endothelial cell injury, in the development of endothelial dysfunction." (PMID 26077715, 2015). "Elevated serum levels of FGF23 might induce a vicious circle after MI, putting additional strain on the heart by salt and volume retention and by endothelial dysfunction caused by suppression of serum vitamin D hormone production." (PMID 25858796, 2015). "FGF-23 levels may provide an additional marker of the morbidity and mortality of Ca*P as it is associated with endothelial dysfunction and cardiovascular outcome." (PMID 23413976, 2013). "FGF-23 has also been associated with endothelial dysfunction." (PMID 23413976, 2013). "However, previous studies have shown that high FGF23 concentration may be associated with endothelial dysfunction and activation of the renin-angiotensin-aldosterone system (RAAS)." (PMID 37593148, 2023). "Elevated phosphate further exacerbates vascular calcification and endothelial dysfunction via the FGF23/Klotho axis and PTH-mediated pathways." (PMID 41166265, 2025). "Novel candidates such as fibroblast growth factor-23 (FGF-23), soluble urokinase plasminogen activator receptor (suPAR), and Klotho have been linked to disease progression, endothelial dysfunction, and cardiovascular events." (PMID 40428218, 2025). "In CKD, where FGF23 is elevated and Klotho is reduced, oxidative stress in endothelial cells results from excessive ROS generated by FGF23, leading to endothelial dysfunction." (PMID 41426862, 2025). "Elevated levels of fibroblast growth factor 23 have been proposed to increase endothelial dysfunction and cardiovascular events." (PMID 39045147, 2024). "Further evidence links FGF-23 to vasoconstriction, decreased NO availability and oxidative stress, which lead to vascular smooth muscle cell and endothelial dysfunction." (PMID 38777916, 2024). "This is a novel finding, it is consistent with the established role of Klotho-FGF23 axis in atherosclerosis, inflammation and endothelial dysfunction found in other humans and animal models." (PMID 37061530, 2023). "High serum FGF23 concentrations are associated with endothelial dysfunction in patients with CKD, and FGF23 has been shown to cause the release of nitric oxide (NO) and the formation of reactive oxygen species (ROS) in human coronary artery endothelial cells." (PMID 36909314, 2023). "Herein, we aimed to assess the effect of M694V homozygosity on the early markers of CVD (FMD and PTX3 for endothelial dysfunction and cIMT and FGF23 for atherosclerosis) in patients with FMF-related amyloidosis." (PMID 35629299, 2022). "Clinical studies revealed a positive correlation between serum FGF23 level and higher left heart ventricle mass with a trend to its hypertrophy, deterioration of coronary arteries structure, and endothelial dysfunction." (PMID 34258392, 2021). "A deregulation of the klotho/FGF23 state observed in CKD has also been linked with cardiovascular disease such as left ventricular hypertrophy, vascular calcification, and endothelial dysfunction." (PMID 32570781, 2020). "In the present cross-sectional study, we correlated marker of endothelial dysfunction (E-selectin), FGF23 and iPTH with serum 25 (OH) vitamin D levels in renal transplant recipients with stable graft function." (PMID 30456544, 2019). "Basic research studies have demonstrated that FGF23 induces the onset and development of atherosclerosis through its effects on vascular calcification and endothelial dysfunction." (PMID 28619026, 2017).
endothelial dysfunction (continued). "Fibroblast Growth Factor 23 is linked to endothelial dysfunction in patients with ESRD and FGF-23 levels have been shown to significantly decrease following successful kidney transplantation." (PMID 27770793, 2016). "FGF23 also contributes to cardiomyocyte hypertrophy, vascular calcification, and endothelial dysfunction." (PMID 27941640, 2016). "A potential shared causal pathway of FGF-23 and ADMA in the development of endothelial dysfunction was recently proposed." (PMID 26077715, 2015). "One potential mechanism by which FGF23 may contribute to CI development is through its effects on vessel inflammation and endothelial dysfunction, which can ultimately lead to thromboembolism and embolic occlusion." (PMID 39096857, 2024). "Excessive FGF23 induced endothelial dysfunction mainly by promoting oxidative stress." (PMID 35794561, 2022). "Measures of increased risk for future CVD events and endothelial dysfunction, including flow-mediated dilatation (FMD), pentraxin-3 (PTX3), and carotid intima-media thickness (cIMT), and fibroblast growth factor 23 (FGF23) as a marker of atherosclerotic vascular disease were compared between groups." (PMID 35629299, 2022). "These uremic toxins may contribute to inflammation, endothelial dysfunction, complement system, and FGF23 pathway, thereby providing insight into the mechanisms that lead to higher CVD mortality and death in HD patients." (PMID 33589722, 2021). "The authors conclude that FGF23 excess may primarily promote oxidative stress and thus endothelial dysfunction." (PMID 32406474, 2020). "Studies in cultured endothelial cells have shown that FGF23 can promote oxidative stress and induce the expression of cell adhesion proteins, suggesting that FGF23 might contribute to endothelial dysfunction." (PMID 29770125, 2018). "Basic studies have suggested that the effects of FGF23 on vascular calcification and endothelial dysfunction might explain the mechanism to some extent." (PMID 28619026, 2017). "Interestingly, we have shown that treatment with 9000 pg/ml FGF23 can induce endothelial dysfunction in mouse aorta and have observed similar dysfunction in a mouse model of CKD." (PMID 27242547, 2016). "Furthermore, we also observed decreased levels of fibroblast growth factor 23 (FGF23) levels in the RCA group (p < 0.001 vs. heparin), remembering that FGF23 is a potent phosphate regulator associated with metabolic changes, endothelial dysfunction, and cardiovascular disease in renal patients." (PMID 38474146, 2024). "Thus, FGF23 excess primarily promoted oxidative stress, and thus endothelial dysfunction." (PMID 32570781, 2020). "Consequently, enhanced circulating as well as locally synthesized FGF23 may promote endothelial dysfunction and further impact on the progression of cardiovascular disease in CKD." (PMID 29892269, 2018). "CKD represents another systemic amplifier of PH-HFpEF, with elevated levels of fibroblast growth factor-23 (FGF-23), oxidative stress, and vascular calcification contributing to endothelial dysfunction and increased PVR." (PMID 40710764, 2025). "In the same study, FGF23 and PTX3 levels, which are markers of atherosclerosis and endothelial dysfunction, respectively, were found to be higher in children with the homozygous M694V genotype." (PMID 40361895, 2025). "Patients with primary glomerulonephritis have a high prevalence of atherosclerosisand endothelial dysfunction, not fully explained by traditional risk factors, butpossibly influenced by the early onset of mineral and bone disorders, marked byincreased serum levels of FGF-23 and chronic inflammation." (PMID 36638246, 2024). "The groups were compared regarding age, FGF23, proteinuria, GFR,flow-mediated dilation and endothelial dysfunction." (PMID 36638246, 2024). "Supporting this finding, patients with a homozygous M694V genotype had higher FGF23 and PTX3 levels, which are surrogate markers for atherosclerosis and endothelial dysfunction, respectively." (PMID 35629299, 2022).
endothelial dysfunction (continued). "Unfortunately, the effect of FGF23 on endothelial dysfunction was not verified in the present study, probably because eGFR was not correlated with FGF23." (PMID 35903313, 2022). "Taken together, it is still questioned whether high FGF23 levels alone are a major driver of vascular alterations in CKD, i.e., endothelial dysfunction and vascular calcification." (PMID 34536161, 2021). "In summary, it is not possible to rule out the presence of other mechanisms related to FGF23, in addition to endothelial dysfunction." (PMID 30971270, 2019). "Studies demonstrated significant relationships between the serum FGF-23 levels and atherosclerotic burden, endothelial dysfunction and arterial stiffness in non-uremic population." (PMID 24180481, 2013).
atherosclerosis (79 papers, 2012 to 2025). A disease characterized by the build-up of fatty material and calcium deposition in the arterial wall resulting in partial or complete occlusion of the arterial lumen. "Fibroblast Growth Factor-23 (FGF-23) is a hormone that has been linked to atherosclerosis and increased cardiovascular risk, including stroke and myocardial infarction." (PMID 40137447, 2025). "An association has been found between elevated levels of FGF23 and atherosclerosis, as well as calcification and thickening of the intima and media of the carotid artery." (PMID 41426862, 2025). "The associations of serum FGF23, α-klotho and FGF23/α-klotho ratio with atherosclerosis in T2DM patients were evaluated using multivariable logistic regression models." (PMID 38622690, 2024). "Studies have also noted higher FGF-23 concentrations in Ps patients compared to healthy subjects, as well as an association between elevated FGF-23 concentrations and a higher prevalence of insulin resistance, dyslipidemia, and atherosclerosis." (PMID 39124628, 2024). "Endothelial injury and dysfunction associated with reduced Klotho levels and elevated FGF23 concentrations have been shown to justify the worsening of atherosclerosis in diabetic patients with PAD." (PMID 37061530, 2023). "Fibroblast growth factor 23 (FGF-23) and its co-receptor, α-Klotho, are key factors in the underlying mechanisms that integrate accelerated atherosclerosis, vascular calcification, mineral disorders, and osteodystrophy." (PMID 35602513, 2022). "Our previous studies revealed that serum FGF23 levels were associated with not only subclinical atherosclerosis but also coronary artery disease, suggesting the involvement of FGF23 in the onset and progression of atherosclerosis." (PMID 28619026, 2017). "Recently, FGF23 has been found to be associated with vascular dysfunction and total body atherosclerosis." (PMID 26459301, 2015). "Klotho-deficient and FGF23-deficient mice exhibit similar phenotypes, characterized by accelerated aging, atherosclerosis, ectopic calcifications, bone demineralization, skin atrophy and emphysema." (PMID 24695641, 2014). "In patients with CKD a strong association has been found between increased serum FGF23 and mortality risk, possibly via enhanced atherosclerosis, vascular stiffness, and vascular calcification." (PMID 24695641, 2014). "Circulating FGF-23 concentration has also been described to be associated with several cardiovascular risk factors and atherosclerosis." (PMID 23555610, 2013). "Higher FGF-23 levels, even in subjects with normal renal function, are associated with cardiovascular risk factors such as vascular dysfunction, atherosclerosis, and left ventricular hypertrophy." (PMID 23555610, 2013). "Recently, higher FGF23 levels have been found to be associated with vascular dysfunction, total body atherosclerosis, and prevalent cardiovascular disease in elderly individuals with normal renal function in community." (PMID 24015259, 2013). "In summary, there is a differential association of circulating FGF-23 concentration with parameters of glucose metabolism, bone density and atherosclerosis that is dependent on iron and obesity status." (PMID 23555610, 2013). "We aimed to explore circulating FGF-23 in association with fatness and insulin sensitivity, atherosclerosis and bone mineral density (BMD)." (PMID 23555610, 2013). "In summary, the associations of circulating FGF-23 concentration with parameters of glucose metabolism, bone density and atherosclerosis are dependent on iron and obesity status-associated insulin resistance." (PMID 23555610, 2013). "FGF23 is also involved in calcium-phosphate metabolism, and high levels of FGF23 may be associated with phosphate imbalance, which is a known risk factor for arterial stiffness and atherosclerosis." (PMID 39096857, 2024). "Thus, FGF-23 is highly associated with atherosclerosis and is a significant risk factor for atherosclerosis and stroke." (PMID 37214403, 2023).
atherosclerosis (continued). "Moreover, high FGF-23 levels have been associated with multiple adverse cardiovascular outcomes, including hypertension, left ventricular hypertrophy, subclinical atherosclerosis and cardiovascular events, and mortality." (PMID 37627287, 2023). "Also, high FGF23 levels can cause a variety of mineral and bone metabolism imbalance diseases in the body, such as atherosclerosis, secondary bone disease, calciphylaxis, and cognitive impairment." (PMID 36649363, 2023). "In addition, one clinical study reveals that FGF-23 is associated with carotid artery intima-media thickness, left ventricular mass, unfavorable cardiac function, and serves as an indicator for atherosclerosis in patients with gestational diabetes." (PMID 33413149, 2021). "For example, FGF-23 is associated with accelerated plaque calcification as well as advanced severity of atherosclerosis in terms of vascular plaque burden, and it functions as a risk factor for coronary artery stenosis as well as adverse cardiovascular outcomes in CHD patients." (PMID 33413149, 2021). "Association of FGF-23 with IR may be another possible mechanism underlying the development and progression of atherosclerosis in DM patients." (PMID 30462803, 2018). "Interestingly, the study describes a positive association between FGF-23 concentrations and the intima-media thickness, another validated measurement of pre-clinical atherosclerosis." (PMID 26462160, 2015). "Moreover, they suggest putative interactions between FGF23 and inflammatory regulatory pathways due to its association with comorbidities of psoriasis like insulin resistance, dyslipidemia, atherosclerosis, or markers of chronic inflammation like interleukin-6, CRP, TNFα, and fibrinogen." (PMID 31847236, 2019). "By using the C-IMT to represent subclinical atherosclerosis, as well as evaluate the CVD risk, the present study found that an elevated serum FGF23 levels could indicate the presence of subclinical atherosclerosis in normoglycemic individuals with a first-degree FHD." (PMID 27698482, 2016). "In vitro experiments demonstrate that FGF23 promotes vascular calcification and arterial stiffness, exacerbating cardiovascular pathologies such as intracranial arteriosclerosis and atherosclerosis [1045, 1046]." (PMID 40407975, 2025). "Numerous pathways such as the transforming growth factor-β (TGF-β) and fibroblast growth factor-23 (FGF-23) are part of the complex pathophysiology of atherosclerosis condition, kidney fibrosis and ischemic nephropathy." (PMID 38551934, 2024). "Our results showed that the serum FGF23 concentration and FGF23/α-klotho ratio were positively associated with T2DM and T2DM combined with atherosclerosis and α-klotho inversely correlated." (PMID 38622690, 2024). "Both FGF23 and the FGF23/Klotho ratio were linearly positively correlated with the occurrence of T2D as well as increased carotid intimal thickness and atherosclerosis in subjects with T2D." (PMID 39272986, 2024). "Second, our cross-sectional study limited us to exploring the causal association of FGF23 and α-klotho with T2DM or atherosclerosis in T2DM patients; therefore, prospective studies are needed to validate the practical relevance of these findings." (PMID 38622690, 2024). "Elevated serum FGF23 levels were positively correlated with increased carotid intima-media thickness (CIMT), a marker of atherosclerosis, while higher α-Klotho levels were inversely associated with CIMT." (PMID 40799848, 2024). "Physiological factors include those influencing atherosclerosis and bone remodeling, such as lipid oxidation, osteoprotegerin, sclerosing protein, metastatic breast cancer cells and fibroblast growth factor 23 (FGF-23)." (PMID 37189364, 2023). "Our objective is to analyze the relationship of FGF23 with disease-related features, including disease activity, damage, and severity, as well as with subclinical atherosclerosis accompanying SLE." (PMID 37627287, 2023).